LTBP2 (latent transforming growth factor beta binding protein 2)
Description:
May play an integral structural role in elastic-fiber architectural organization and/or assembly.
Synonyms: C14orf141; LTBP3; GLC3D; MSPKA; MSTP031; WMS3
Tractability: Antibody: UniProt places it where antibodies can reach, with high confidence; its Gene Ontology location is reachable by antibodies, with high confidence; UniProt predicts a signal peptide or a membrane-spanning region.
Gene: Protein-coding gene on chromosome 14 (74,498,183 to 74,612,378, reverse strand). Ensembl gene ENSG00000119681.
Subcellular location: Secreted, extracellular space, extracellular matrix
Pathways (Reactome):
Extracellular matrix organization: Molecules associated with elastic fibres
Signal Transduction: TGF-beta receptor signaling activates SMADs
Gene Ontology:
Molecular function: protein binding; extracellular matrix structural constituent; microfibril binding; calcium ion binding
Biological process: supramolecular fiber organization; protein secretion; protein targeting; transforming growth factor beta receptor signaling pathway; establishment of protein localization to extracellular region
Cellular component: extracellular exosome; extracellular matrix; extracellular region; elastic fiber; non-collagenous component of interstitial matrix; transforming growth factor beta complex; microfibril
Genetic constraint (gnomAD): Loss-of-function variants: 103 observed, 203.88 expected, observed/expected ratio (o/e) 0.51, 90% interval 0.43 to 0.6. The upper end of that interval is the gene's LOEUF score, 0.6, which puts it in group 2 of 6, group 1 being the genes least tolerant of losing a copy. Missense variants: 2,303 observed, 2,462.3 expected, observed/expected ratio (o/e) 0.94, 90% interval 0.9 to 0.97. Synonymous variants: 1,001 observed, 1,004.2 expected, observed/expected ratio (o/e) 1, 90% interval 0.95 to 1.05.
Gene-disease validity (ClinGen):
ClinGen rates the evidence that LTBP2 causes each of these diseases.
glaucoma 3, primary congenital, D (autosomal recessive): Definitive.
Homologues: Orthologues: chimpanzee LTBP2 (99% identical), macaque LTBP2 (97% identical), dog LTBP2 (86% identical), pig LTBP2 (85% identical), rabbit LTBP2 (82% identical), rat Ltbp2 (81% identical), guinea pig LTBP2 (80% identical), mouse Ltbp2 (80% identical). Paralogues in human: LTBP1 (38% identical), LTBP4 (33% identical), LTBP3 (26% identical).
Diseases named in the same sentence as LTBP2 in open-access papers:
LTBP2 is named in the same sentence as 110 diseases in open-access papers, as found by Europe PMC text mining. Sharing a sentence is not in itself a finding about the gene and the disease. The quoted sentences say what the papers report.
glaucoma (28 papers, 2011 to 2025). Increased pressure in the eyeball due to obstruction of the outflow of aqueous humor. "Cross-referencing with human genome-wide association studies data revealed overlap with glaucoma-associated genes (LTBP2, LOXL1, COL11A1, VCAM1), alongside reduced expression of Angpt and Lmx1b, linked to ocular hypertension." (PMID 41443436, 2025). "Mutations in LTBP2 are known to cause the Weill-Marchesani syndrome and a Weill-Marchesani-like syndrome, which include glaucoma in their clinical presentation." (PMID 30380740, 2018). "In primary open angle glaucoma, five putative disease-contributing or risk factor mutations in LTBP2 were observed in 42 Iranian patients." (PMID 29751740, 2018). "Recently, in three consanguineous Saudi families with congenital megalocornea with zonular weakness and childhood lens-related secondary glaucoma it was found that ocular anomaly segregated with homozygous LTBP2 mutations." (PMID 29751740, 2018). "These cats not only further establish a role for LTBP2 as a glaucoma causing gene but also provide a spontaneous animal model allowing further investigation of the pathophysiological mechanisms of PCG as well as potential treatment approaches." (PMID 27149523, 2016). "Contrary to other known genes causing PCG (CYP1B1) or POAG (MYOC, OPTN, and WDR36), one can easily consider a plausible cellular and molecular basis for association between LTBP2 and the glaucoma phenotype." (PMID 23401661, 2013). "LTBP2 dysregulation has been linked to eye diseases in numerous studies, including glaucoma." (PMID 38928268, 2024). "To date, mutations in the LTBP2 gene have been associated with several types of glaucoma." (PMID 29751740, 2018). "Detecting mutations helps to determine mode of inheritance; for example, mutations in CYP1B1 and LTBP2 cause recessive traits, whereas glaucoma caused by other known genes may be inherited in a dominant fashion." (PMID 24665880, 2014). "This notwithstanding, the consequences of LTBP2 mutations for regulating TGF-β signaling may also be relevant to the etiology of glaucoma." (PMID 23401661, 2013). "In the current study we clinically characterize eight patients from three consanguineous Saudi families with congenital megalocornea and childhood secondary glaucoma from spherophakia and/or ectopia lentis and confirm its recurrent association with LTBP2 mutations." (PMID 22025892, 2011). "The finding of elevated AH TGF-β2 concentrations in this feline model, although generalizable to other forms of glaucoma, may be most directly relevant to human glaucoma due to LTBP2 mutations, contributing insight into the pathology of this complex, poorly understood genetic disease." (PMID 37459065, 2023). "Although the clinical phenotype of this feline glaucoma model has been rigorously characterized, the underlying aqueous outflow pathway pathophysiology has not yet been fully delineated in either this large animal model or in human glaucoma with LTBP2 mutations." (PMID 37459065, 2023). "Other genes involved in microfibril function, such as LOXL1 and LTBP2, are associated with human glaucoma, lending further support to our microfibril hypothesis of glaucoma." (PMID 30406200, 2018). "Moreover, patients diagnosed as primary congenital/infantile glaucoma from LTBP2 mutations had poorer results from angle surgery as children, which would be expected if the actual diagnosis were congenital megalocornea with childhood secondary lens-related glaucoma." (PMID 22025892, 2011). "In 8 (33%) children with childhood glaucoma one of the following congenital glaucoma associated genes (CYP1B1, FOXC1, LTBP2 and TEK) was confirmed by the genetic examination." (PMID 35144644, 2022). "Several of the differentially expressed genes have previously been reported to be associated with elevated IOP and/or glaucoma, including MYOC, ADAMTS10, LTBP2, LOXL1, TGFBR3, CYP1B1, and EFEMP15,28,43–45." (PMID 34385434, 2021).
glaucoma (continued). "We identified three novel mutations in glaucoma families using WES; two in the LTBP2 gene and one in the PXDN gene." (PMID 27409795, 2016). "The possible contribution of LTBP2 to primary open angle glaucoma (POAG; OMIM 137760) and pseudoexfoliation syndrome (PEX; OMIM 177650) is addressed in this study." (PMID 23401661, 2013). "Microscopy was performed on the skin of a patient with PEX syndrome whose condition developed into PEX glaucoma during the course of the study and on the skin of her son previously identified with PCG who harbored the same LTBP2 mutation." (PMID 23401661, 2013). "In 33% of children with glaucoma mutations in the CYP1B1, FOXC1, LTBP2 and TEK genes were found." (PMID 35144644, 2022). "The mechanism behind the pathogenic involvement of the LTBP2 gene in glaucoma is not clearly established, but it has been demonstrated that the LTBP2 protein is associated with elastic fibers in developing elastic tissues." (PMID 27409795, 2016). "Given that PEX is a fibrotic disorder often associated with glaucoma (PEXG) and that LTBP2 is a component of PEX material, the possibility that LTBP2 mutations may be associated with this disease was also considered." (PMID 23401661, 2013). "Among the five known glaucoma-causing genes– MYOC (myocilin), CYP1B1 (cytochrome P450, family 1, subfamily B, polypeptide 1), OPTN (optineurin), WDR36 (WDR36), and LTBP2 (latent transforming growth factor beta binding protein 2)–all except WDR36 were identified in three of the studies." (PMID 22312193, 2012). "LTBP2 (latent transforming growth factor beta binding protein 2), a primary glaucoma causing gene, was not probed on the arrays." (PMID 21617755, 2011). "The combination of large corneas with elevated IOP is very suspicious for primary congenital/infantile glaucoma in a child or in an adult; however, for this unique LTBP2-related phenotype the megalocornea is unrelated to glaucoma with the primary problem being spherophakia and/or ectopia lentis." (PMID 22025892, 2011). "Although LTBP2 is known to be highly and preferentially expressed in anterior segment ocular tissues and known to play a role in extracellular matrix (ECM) assembly, the pathophysiology of glaucoma due to LTBP2 mutations in humans remains unclear." (PMID 37459065, 2023). "In secondary childhood glaucoma cases, alterations in CYP1B1 (25%), SOX11 (13%), FOXC1 (13%), GJA8 (13%) and LTBP2 (13%) were detected." (PMID 35011756, 2021). "myocilin (MYOC), optineurin (OPTN), WDR36 and neurotrophin-4 (NTF4) in primary open angle glaucoma (POAG) and CYP1B1 and LTBP2 in congenital and developmental glaucomas." (PMID 21150032, 2011). "Congenital Glaucoma can be caused by the CYP1B1, LTBP2, TEK, and two loci of uncertain function which were not investigated in this research." (PMID 39480826, 2024). "Analysis of the combined RNA-Seq and ChIP-Seq data showed that the transcription of several of the differentially expressed genes with roles in TM, IOP, and glaucoma, were directly regulated by GLIS1 and included MYOC, LTBP2, CHI3L1, HMGA1, CYP1B1, and LOXL1-4." (PMID 34385434, 2021). "Most commonly, genetic testing reveals mutations in CYP1B1, LTBP2, TEK (in PCG), MYOC, TBK1, OPTN (in JOAG) and a variety of mutations in glaucoma associated with non-acquired ocular anomalies, FOXC1, PITX2 (in Axenfeld–Rieger Anomaly And Syndrome), PAX6 (in aniridia), and LTBP2 and CPAMD8." (PMID 39941238, 2025). "In addition, we identified several transcriptional targets of GLIS1 in TM cells that previously have been implicated in TM-related functions, IOP homeostasis, and ocular hypertension/glaucoma, including MYOC, ADAMTS10, LTBP2, LOXL1, TGFBR3, CYP1B1, and EFEMP15,28,43,44." (PMID 34385434, 2021). "However, altered LTBP2 expression, through its impact on assembly of micofibrils and ECM composition can also influence the bioavailability of TGFβ, which is known to play a complex and important role in glaucoma pathogenesis." (PMID 27149523, 2016).
primary congenital glaucoma (12 papers, 2010 to 2025). "Of the genes known to cause primary congenital glaucoma or anterior segment dysgenesis, LTBP2 and TEK showed marked differentiation from normal control morphology." (PMID 38682030, 2024). "Among the two causative genes (CYP1B1 and LTBP2) of primary congenital glaucoma (PCG), CYP1B1 is found to be highly mutated and responsible for the etiology of PCG patients worldwide." (PMID 36518267, 2022). "In patients with microspherophakia or other ocular anomalies, such as megalocornea, myopia, congenital primary glaucoma or secondary glaucoma, mutations have been found in the LTBP2 gene." (PMID 29751740, 2018). "Mutations in LTBP2 have previously been shown to be the cause of primary congenital glaucoma (PCG) and other disorders that often manifest as secondary glaucoma." (PMID 23401661, 2013). "Homozygous nonsense mutations in the LTBP2 gene were identified in four consanguineous Pakistani families and in eight of 15 Gypsy individuals with primary congenital glaucoma." (PMID 23378721, 2013). "In previous studies, many mutation sites in LTBP2 have been proved to have some functions in the development of primary congenital glaucoma (c.3028G > A, p.Asp1010Asn; c.3427delC, p.Gln1143Argfs*35), cardiomyocytes (c.2206G > A, p.Asp736Asn), and lung fibroblast-to-myofibroblast differentiation." (PMID 36482906, 2022). "Here we report a mutation in LTBP2 that causes primary congenital glaucoma (PCG) in domestic cats." (PMID 27149523, 2016). "LTBP2 (OMIM 602091), the gene encoding latent transforming growth factor (TGF)-beta binding protein 2, was identified in 2009 as a gene causing primary congenital glaucoma (PCG; OMIM 231300)." (PMID 23401661, 2013). "Axenfeld–Rieger syndrome and primary congenital glaucoma share some causative genes (FOXC1 and CYP1B1) that may also induce other subtypes of ASD (aniridia, iris hypoplasia, and Peters anomaly), while the LTBP2 gene is confined to primary congenital glaucoma." (PMID 40364033, 2025). "In primary congenital glaucoma (PCG), null mutations in LTBP2 were reported in four consanguineous families of Gypsy ethnicity from Pakistan, in three unrelated Iranian families, and, more recently, two novel mutations in consanguineous families of Pakistani ancestry were identified using WES." (PMID 29751740, 2018). "A number of chromosomal loci associated with primary congenital glaucoma (PCG) have been identified in humans (OMIM 231300, 600975, 613085, and 613086) and mutations in the cytochrome P450 gene, CYP1B1, and LTBP2 gene at two of these loci were identified in families segregating PCG." (PMID 27149523, 2016). "LTBP2 gene mutations are not involved in the pathogenesis of primary congenital glaucoma in our patients." (PMID 23378721, 2013). "In the present study, we screened all the exons with intron-exon boundaries of the LTBP2 gene in 54 unrelated patients with primary congenital glaucoma who were either negative or heterozygous for CYP1B1, MYOC, and FOXC1 gene mutations and 50 healthy controls." (PMID 23378721, 2013).
congenital glaucoma (10 papers, 2011 to 2025). "LTBP2 levels were also increased consistently with Dex treatment whose mutation has been associated with congenital glaucoma in humans and cats." (PMID 35557957, 2022). "The spectrum of clinical disease associated with mutations in LTBP2 is rather broad and includes megalocornea, microspherophakia and ectopia lentis, as well as congenital glaucoma." (PMID 27149523, 2016). "We did not identify pathogenic or likely pathogenic variants in other genes known to cause congenital glaucoma, including rare variants (allele frequency <0.001) in ANGPT1, CPAMD8, CYP1B1, MYOC, LTBP2, PITX2, SVEP1, and TEK." (PMID 36453543, 2022). "For a better understanding of the pathogenesis and genetic mechanism of congenital glaucoma, more studies involving the LTBP2 gene in sporadic cases and families with PCG should be conducted." (PMID 23378721, 2013). "In the gene knockout groups with genes related to congenital glaucoma, GMDS, FOXC1, LTBP2, TEK, and CYP1B1, no distinct patterns were observed in the transcriptome of these gene knockout groups." (PMID 38272457, 2024).
ectopia lentis (10 papers, 2011 to 2025). "This proposal is consistent with observations that mutations in the human LTBP2 gene can cause interalia ectopia lentis and that LTBP2-deficient mice develop ectopia lentis." (PMID 41354343, 2025). "Genetic variants were identified in four genes: FBN1 (associated with Marfan syndrome and cardiovascular complications; n = 6), ADAMTSL4 (associated with non-syndromic ectopia lentis; n = 2), LTBP2 (n = 1) and ASPH (n = 1)." (PMID 37107549, 2023). "A previous study showed ASPH‐mediated hydroxylation of FBN1/LTBP2 may be associated with ectopia lentis." (PMID 33217155, 2021). "Similarly, LTBP2-deficient mice develop ectopia lentis, typically by 4 months of age." (PMID 39768188, 2024). "All the genes associated with ectopia lentis phenotypes to date, (ADAMTSL4, FBN1, LTBP2, ADAMTS10, ADAMTS17) included in the clinical exome employed, revealed several genetic variants in these genes." (PMID 29751740, 2018). "A normal functional role of LTBP2 in the fibrillin pathway is presumably why mutations in LTPB2 cause congenital megalocornea and early childhood ectopia lentis with a tendency for complete lens dislocation." (PMID 22025892, 2011). "Similarly, the ectopia lentis phenotype in LTBP2-null mice can be rescued by overexpressing the structurally related protein LTBP4." (PMID 39768188, 2024). "Recent studies of murine models of ectopia lentis have shown that LTBP-2 plays an essential role in the maintenance of ciliary zonule fiber stability and could therefore be a candidate for forming links between microfibrils." (PMID 30120953, 2018). "Autosomal recessive Weill–Marchesani (OMIM # 613195)—clinical features in this form can overlap autosomal-dominant Weill–Marchesani syndrome, but genes involved in the condition are: ADAMTS10, ADAMTS17, and LTBP2 (described in one family, without Ectopia Lentis)." (PMID 37443678, 2023).
Microspherophakia (8 papers, 2013 to 2025). Microspherophakia is a rare congenital anomaly characterized by the abnormal spherical shape of the crystalline lens. "We describe the first case of a microspherophakia phenotype associated with a novel homozygous mutation in the LTBP2 gene in a consanguineous Caucasian family by means of NGS technology." (PMID 29751740, 2018). "The present work describes an isolated microspherophakia phenotype due to a new homozygous mutation in the LTBP2 gene in a Spanish consanguineous family." (PMID 29751740, 2018). "This is the first report of the association of a mutation in the LTBP2 gene and isolated microspherophakia in Caucasians." (PMID 29751740, 2018). "The present work describes for the first time the association of a mutation in the LTBP2 gene (c.5439_5440insA) with an isolated microspherophakia phenotype in a consanguineous Caucasian family." (PMID 29751740, 2018). "Recently, homozygous mutations in LTBP2 were reported in a syndrome of megalocornea, microspherophakia (small spherical lens), lens dislocation, and secondary glaucoma developing after age 3 years and in isolated microspherophakia/lens dislocation." (PMID 23378721, 2013). "These new data highlight the value of investigating the involvement of the LTBP2 gene in cases with an isolated microspherophakia phenotype." (PMID 29751740, 2018). "Because the interaction between the LTBP2 and the Fibrillin-1 proteins is close to this LTBP2 C-terminal region, we could speculate that the instability of the zonular fibers characteristic in microspherophakia is due to the loss of the association between these two proteins." (PMID 29751740, 2018). "Isolated microspherophakia (IM), without any other ocular feature, has been recently been linked to the LTBP2 gene." (PMID 29751740, 2018). "An altered regulation due to the presence of an abnormal LTBP2 protein might thus prevent normal growth of the lenses, characteristic of the microspherophakia phenotype." (PMID 29751740, 2018). "Unlike in human WMS3 patients, microspherophakia has not been reported in LTBP2-null mice." (PMID 39768188, 2024).